RNU6-649P (RNA, U6 small nuclear 649, pseudogene)
Gene: Small nuclear RNA gene on chromosome 2 (4,945,277 to 4,945,383, forward strand). Ensembl gene ENSG00000207192.
Homologues: Orthologues: chimpanzee U6 (100% identical), macaque U6 (86% identical), dog U6 (59% identical). Paralogues in human: RNU6-1145P (87% identical), RNU6-38P (85% identical), RNU6-698P (85% identical), RNU6-1316P (84% identical), RNU6-188P (84% identical), RNU6-378P (84% identical), RNU6-434P (84% identical), RNU6-664P (84% identical), RNU6-74P (84% identical), RNU6-831P (84% identical), RNU6-891P (84% identical), RNU6-1075P (83% identical), and 1286 more.